IL7 (interleukin 7)
Diseases named in the same sentence as IL7 in open-access papers (continued):
Sharing a sentence is not in itself a finding about the gene and the disease.
Sepsis (continued). "Immunization of mice with the fungal antigen GliT 30 days after sepsis induction revealed a strongly reduced number of GLiT-specific Th-cells in post-septic mice, regardless of whether they had been treated with IL-7 or not." (PMID 30730978, 2019). "Given that MDSCs from non-treated and IL-7-treated septic mice strongly inhibited T-cell proliferation, the sustained presence of large numbers of these cells for months after sepsis strongly suggests that the MDSCs contribute to the lasting immunosuppression in sepsis survivors." (PMID 29466409, 2018). "However, the rate of lymphocytes varied significantly between days 1 and 5 in both sepsis survivors and non-survivors, with a notably lower percentage observed in non-survivors, meaning that endogenous IL-7 is insufficient to restore lymphocyte homeostasis in sepsis." (PMID 40005375, 2025). "Our study found a negative correlation between IL-7 and Th cells (CD4+) and Tc cells (CD8) on day 1 and day 5 in the sepsis survivors’ group." (PMID 40005375, 2025). "In contrast, no increase in total CD4+ T cells was observed 1 week post sepsis induction in IL-7-treated septic mice, indicating a preferential expansion of Foxp3+CD25+ Tregs upon IL-7 treatment." (PMID 29466409, 2018). "On the other hand, the positive correlation between IL-7 levels and B cells (CD19+) observed in the non-survivor sepsis group could be attributed to IL-7’s indirect effects." (PMID 40005375, 2025).
autoimmune disease (62 papers, 2009 to 2025). A disorder resulting from loss of function or tissue destruction of an organ or multiple organs, arising from humoral or cellular immune responses of the individual to their own tissue constituents. "IL-7, essential for B-cell progenitors, has associations with autoimmune diseases such as rheumatoid arthritis." (PMID 41030257, 2025). "Increased physiological levels of IL-7 affect joint inflammation, osteoclastogenesis, and neovascularization associated with autoimmune diseases." (PMID 36911710, 2023). "IL-7 cytokine is necessary for the proliferation and survival of pathogenic Th17 cells, and has a promotional role in autoimmune diseases such as experimental autoimmune encephalomyelitis.." (PMID 38035087, 2023). "Given the association of CTACK in other autoimmune diseases and the important role of other cytokines (e.g., IL-23, IL-7, and TNF-α) in AS, we believe that it is valuable to further explore the connection between CTACK levels and AS pathogenesis." (PMID 38173728, 2023). "Homeostatic cytokines such as interleukin-7 (IL-7) have been implicated in the aetiology of autoimmune disease." (PMID 35015072, 2022). "Interleukin-7 (IL-7) signaling modulates T cell activity and is implicated in numerous autoimmune diseases." (PMID 33755713, 2021). "The inflammasome activation and the IL-7 and ErbB2-ErbB3 pathways conferred susceptibility to other autoimmune diseases like SLE and psoriasis or T1D including in another Brazilian cohort." (PMID 35058920, 2021). "An upregulation of IL7, a lymphoid haematopoietic growth factor, recorded by us, has been shown to be associated with autoimmune diseases, such as multiple sclerosis and diabetes." (PMID 33985567, 2021). "IL-7/IL-7R signaling, which regulates lymphocyte growth and survival, has been implicated in the development of malignancies and autoimmune diseases." (PMID 28878234, 2017). "It favor of the previous assumption are data indicating that dysregulation of the IL-7/IL-7R axis has long been implicated in autoimmune diseases, such as type 1 diabetes, multiple sclerosis and rheumatoid arthritis." (PMID 26448779, 2015). "Elevated IL-7 in the target tissues is closely associated with multiple autoimmune disorders, including Sjögren’s syndrome (SS)." (PMID 24147035, 2013). "However, in contrast to VEGF-C, IL-7 has also been linked to the pathogenesis of a number of autoimmune diseases." (PMID 31406267, 2019). "Besides elevated IL-21, reduced IL-7 levels correlated with an increased risk of autoimmune disease after alemtuzumab." (PMID 26204829, 2015). "Furthermore, IL-7 and its receptor have been implicated in several autoimmune diseases like rheumatoid arthritis (RA), psoriasis, spondylarthritis, inflammatory bowel’s disease (IBD) multiple sclerosis (MS), and recently primary Sjögren’s Syndrome (pSS)." (PMID 24740301, 2014). "Excessive IL-7 production and activities in the target tissues are linked to multiple autoimmune disorders and blockade or genetic ablation of IL-7 prevents or reverse these autoimmune diseases." (PMID 24147035, 2013). "And high levels of IL-7 are associated with autoimmune diseases such as rheumatoid arthritis, whether boosting IL-7 would have similar side effects as inhibiting TGF-β or more is not known, which may limit the application of IL-7 boosting strategy to IPF patients." (PMID 38783236, 2024). "This review aims to summarize the current understanding of the role of IL-7 in autoimmune diseases, focusing on its mechanisms of action, implications for disease progression, and potential therapeutic applications." (PMID 40313966, 2025). "The mechanism of action of IL-7 in autoimmune diseases is complex and diverse, which involves multiple immune cell subsets and signaling pathways." (PMID 40313966, 2025).
autoimmune disease (continued). "Growing evidence has demonstrated that IL-7 is involved in the pathogenesis of various autoimmune diseases including rheumatoid arthritis (RA), systemic lupus erythematosus (SLE), type 1 diabetes (T1D) and multiple sclerosis (MS)." (PMID 40313966, 2025). "As a result, IL-7 becomes a highly promising target for studying the pathogenesis and treatment strategies of autoimmune diseases." (PMID 40313966, 2025). "Next, the expression changes of IL-7 in different types of autoimmune diseases and the specific mechanisms involved in the occurrence and development of the disease were discussed." (PMID 40313966, 2025). "IL-7 has the ability to stimulate the proliferation of Th17 and Th1 cells in some autoimmune disease." (PMID 40313966, 2025). "As an important member of the cytokine family, interleukin-7 (IL-7) has received extensive attention in the research field of autoimmune diseases in recent years." (PMID 40313966, 2025). "Understanding the complex mechanisms of IL-7 in autoimmune diseases is essential for the development of effective and targeted therapies." (PMID 40313966, 2025). "Given the well-established role of IL-7 in autoimmune processes, the utility of anti-IL-7R therapy has been explored in various autoimmune diseases, yielding promising preclinical study results." (PMID 40642097, 2025). "IL-7 is thought to support aberrant immune activity in autoimmune diseases such as diabetes mellitus and multiple sclerosis." (PMID 39713769, 2024). "The presence of IL7 depletion indicates a dysregulation of lymphocyte homeostasis, which is common in autoimmune diseases like rheumatoid arthritis." (PMID 39563367, 2024). "Recently, there has been increasing evidence that IL-7 is involved in a multitude of autoimmune disorders, such as type I diabetes, multiple sclerosis, rheumatoid arthritis, and systemic lupus erythematosus." (PMID 39315093, 2024). "Aberrant expression of IL-7 and soluble IL-7Rα in plasma is indicative of pathological T cell immunity in chronic viral, inflammatory, and autoimmune diseases." (PMID 38408097, 2024). "The development of drugs targeting the IL-7 gene for autoimmune diseases and cancer seems very promising, particularly the use of recombinant IL-7 proteins, IL-7 gene vaccines, IL-7 receptor antagonists, and IL-7 signalling pathway blockers." (PMID 38675377, 2024). "IL-7 plays an important role in T-cell development, homeostasis, and immune tolerance, suggesting the use of the IL-7/IL-7Rα pathway as a target for autoimmune disease treatment." (PMID 37370001, 2023). "IL-7 is involved in the pathogenesis of chronic inflammatory diseases and is targeted in patients with autoimmune diseases." (PMID 35874706, 2022). "This suggests that PTSD is associated with increases in IL-7 in the AN sample, which is consistent with previous findings of elevations in IL-7 in individuals with PTSD and autoimmune disease, compared to autoimmune disease alone." (PMID 34442458, 2021). "In a recent study of alopecia areata, a T cell-mediated autoimmune disease of the hair follicles, IL-7 blockade was found to suppress acute inflammatory responses of the disease, while relatively sparing Treg." (PMID 34276694, 2021). "There is increasing evidence which implicates aberrant IL-7/IL-7R signaling in the pathogenesis of numerous autoimmune diseases, such as rheumatoid arthritis, type I diabetes, MS, systemic lupus erythematosus and Primary Sjögren’s Syndrome." (PMID 33755713, 2021). "Here, we first discuss the major pathophysiological roles of TSLP and IL-7 in autoimmune diseases, inflammation and cancer." (PMID 32849527, 2020). "The possibilities of ADCs in combination with IL-7R have previously been considered after confirming the involvement of IL-7 signaling in steroid-resistance when addressing the treatment of autoimmune diseases and cancers." (PMID 32849527, 2020).
autoimmune disease (continued). "IL-7 is a key factor in T cell immunity and common variants at IL7R, encoding its receptor, are associated with autoimmune disease susceptibility." (PMID 31594933, 2019). "In line with this, elevated IL-7 levels are associated with development of aGVHD after myeloablative HSCT and is increased in autoimmune diseases." (PMID 29456530, 2018). "Interest in the functional effect of IL-7 in autoimmune diseases has grown in recent years due to the fact that enhanced IL-7 level fuels the proliferation of autoreactive T cells." (PMID 28578701, 2017). "In this respect, murine models of autoimmune diseases treated with inhibitors of IL-7/IL-7Rα signaling show preventive or therapeutic efficacy." (PMID 28356069, 2017). "This emphasizes the additional benefits of TSLP-signalling blockade in conjunction with blockade of IL-7-signalling as a therapeutic strategy in rheumatoid arthritis and possibly other autoimmune diseases." (PMID 26110994, 2015). "Elevated levels of IL-7 have been found in autoimmune diseases, like pSS, RA, JIA, psoriatic arthritis and MS." (PMID 24740301, 2014). "In the inflamed tissues of patients with autoimmune diseases, increased IL-7 production and IL-7 receptor (IL-7R) expression by tissue cells and immune cells have been documented." (PMID 24740301, 2014). "The regulation of IL-7 gene expression by external signals in autoimmune disease settings is not well understood." (PMID 24147035, 2013). "Studies in recent years have shown that elevated IL-7 levels correlate with the onset of many autoimmune diseases in human, and blockade of IL-7 in a number of mouse models abolishes or alleviates the diseases before or after disease onset." (PMID 24147035, 2013). "The review further delves into the role of IL-7 in different autoimmune diseases." (PMID 40313966, 2025). "IL-7 and its receptor play a crucial role in the pathogenesis of autoimmune diseases." (PMID 40313966, 2025). "IL-7 may play a role in the progression of autoimmune diseases by promoting the expansion of self-reactive clones." (PMID 40313966, 2025). "IL-7, a member of the IL-2 family, is considered to affect aberrant immune activity in autoimmune diseases, such as diabetes and multiple sclerosis, and chronic inflammatory diseases, such as rheumatoid arthritis, ankylosing spondylitis, and inflammatory bowel disease, by binding to IL-7R." (PMID 40240976, 2025). "However, an increasing number of studies have shown that IL-7 also plays a complex and important role in the pathological process of autoimmune diseases." (PMID 40313966, 2025). "Previous studies showed that targeting components in IL-7 signaling pathways may have potential significance for treating multiple autoimmune diseases." (PMID 39315093, 2024). "These include Il-7 and its receptor Il7R, CD226, CAPSL, and CLEC16A, which appear to be attractive candidates for further studies to explore the pathogenic mechanisms and potential therapeutic options for autoimmune diseases." (PMID 38612837, 2024). "IL-7 is essential for chronic inflammatory and autoimmune diseases." (PMID 36084127, 2022). "Our work may also be placed in the context of recent clinical applications of IL-7 signal blockade for the treatment of leukemia, lymphoma and autoimmune diseases." (PMID 34276694, 2021). "IL7 provides survival signals to T cells and plays an important role in autoimmune diseases." (PMID 34658852, 2021). "Accordingly, IL-7 is expressed in inflamed tissues of patients with (rheumatic) autoimmune diseases, where it can be produced by several cell types (including macrophages, dendritic cells, and fibroblasts) and favor pathogenic Th1- and Th17-associated cytokine secretion." (PMID 29506153, 2018). "IL-7 enhances inflammation in various autoimmune disorders, including rheumatoid arthritis (RA) where it is increased in the synovial fluid (SF) and stimulates T-cells to produce various cytokines including tumor necrosis factor (TNF)-α, interferon (IFN)-γ, and IL-17." (PMID 26110994, 2015).
autoimmune disease (continued). "Recent studies demonstrated that IL-7 is overexpressed in several autoimmune diseases." (PMID 25533722, 2014). "This information will enable future in-depth studies on the regulation of IL-7 production and its functions in pSS and other autoimmune disorders and will facilitate the development of new therapeutic strategies to combat these diseases by inhibiting IL-7 production and activity." (PMID 24147035, 2013). "Moreover, similar to the other autoimmune disorders, the promoting effects of IL-7 on pSS are underpinned by enhanced Th1 and Tc1 responses in the target organs." (PMID 24147035, 2013). "Furthermore, recent studies suggest that effects on the IL7/IL7R pathway may be important in the treatment of autoimmune diseases." (PMID 38612837, 2024). "In addition, the IL-7 axis is involved in GM-CSF production by Th subsets that could lead to autoimmune diseases such as type 1 diabetes mellitus." (PMID 36012236, 2022). "Therefore, targeting components in IL-7 signaling pathway may be of therapeutic benefit for these autoimmune diseases." (PMID 33755713, 2021). "Our results suggest the addition of IL-7 during antigenic stimulation with allogeneic dendritic cells can promote the expansion of CD62L+Th-2+CD4+ human iNKT cells that can be used as novel immunotherapeutic to control excessive inflammation to treat various autoimmune diseases." (PMID 33329531, 2020). "Targeting of IL-7:IL-7Rα for therapeutic development in autoimmune diseases has mainly focused on the development of monoclonal anti-IL-7Rα antibodies which could be beneficial by blocking IL-7Rα and subsequently attenuating the action of effector T cells but retaining the Treg activity." (PMID 32849527, 2020). "However, the picture may be different in diseases characterized by high levels of circulating IL-7, including chronic infections and autoimmune diseases." (PMID 28473831, 2017). "The notion that low IL7R expression levels are beneficial for reaching old age healthily corresponds with previous observations that autoimmune disease patients express increased levels of the IL receptor/ligand complex genes and that antagonizing IL7 or IL7R may offer possible treatment." (PMID 26566388, 2015). "Finally, IL7 is an important immune system gene involved in T and B cell production and has been implicated in other autoimmune diseases, notably rheumatoid arthritis, but not MS." (PMID 20546594, 2010). "Stimulation of the receptor for Interleukin 7 (IL7R) has been shown to play an important role in the development and progression of autoimmune diseases." (PMID 38612837, 2024). "As a member of the Interleukin family, Interleukin 7 (IL7) play vital roles in hematopoiesis and the development of T lymphocytes, as well as the inflammation, autoimmune diseases and hematological cancers." (PMID 35874754, 2022). "In conclusion, our data reinforce that in humans, the concept of blocking IL-7 in autoimmunity may have important therapeutic effects, as recently demonstrated in the collagen-induced arthritis model as well as in several other autoimmune disease animal models and in melanoma." (PMID 25533722, 2014). "Psoriasis is an autoimmune disorder for which the contribution of the IL-7/IL-7Rα signalling pathway has not been investigated to date." (PMID 31406267, 2019). "Given the role of IL-7 in T cell growth factor activity, it is not a surprise that increased levels of IL-7 have been reported in several autoimmune diseases such as multiple sclerosis, rheumatoid arthritis, type 1 diabetes, and systemic lupus erythematosus." (PMID 28578701, 2017). "The culture system used in this study also demonstrates that in an antigen-independent environment locally overexpressed IL-7 and TLR7, as has been shown in several autoimmune diseases, are sufficient to trigger immunoglobulin production, which makes this a relevant observation." (PMID 24740301, 2014).
autoimmune disease (continued). "On a long run, such non-antigen specific stimuli can lead to autoimmune diseases as demonstrated in IL-7 transgenic mice." (PMID 22194871, 2011). "We reported that autoimmune disease in gp130 mutant mice is caused by increased homeostatic proliferation of CD4+ T-cells, which is due to elevated production of IL-7 by non-hematopoietic cells as a result of IL-6 family cytokine-gp130-STAT3 signaling." (PMID 19228423, 2009). "Seeing that the absence of IL-7 mediated signaling leads to lymphopenia, a role of its regulation in autoimmune diseases could be implied." (PMID 32849527, 2020).